IL1B (interleukin 1 beta)
Diseases named in the same sentence as IL1B in open-access papers (continued):
Sharing a sentence is not in itself a finding about the gene and the disease.
duodenal ulcer (7 papers, 2010 to 2025). An ulcer in the duodenal wall. "We further analyzed Smad 7, NFkB, IL1B and gastrin expression in antral gut biopsy samples of patients with H. pylori associated duodenal ulcer and normal individuals." (PMID 21445336, 2011). "The -31C promoter polymorphism of IL1B has been reported to be associated with H. pylori mediated duodenal ulcer in various populations." (PMID 21445336, 2011). "Interleukin-1β (IL1β) and interleukin-1 receptor antagonist (IL1RN) gene polymorphisms have been found to be associated with increased risk of AG, GC and duodenal ulcer (DU), but contradictory results have been reported." (PMID 27785255, 2013). "We observed that individuals with duodenal ulcer had significantly lower levels of IL1B, Smad 7, NFkB and corresponding higher level of gastrin expression." (PMID 21445336, 2011). "The difference in IL1B expression in H.pylori infected asymptomatic individuals (Hp+ U−) in comparison to duodenal ulcer patients (HP+U+) can be attributed to the difference in genetic make up of these individuals as reported by various association studies." (PMID 21445336, 2011). "Furthermore, it was shown that gastric epithelium significantly contributed to the antral IL-1β and IL-6 response from H. pylori-infected duodenal ulcer patients and asymptomatic carriers." (PMID 31065302, 2019). "Literature search did not reveal any article investigating IL-1β in sera of patients with bleeding duodenal ulcer in relation to H. pylori infection." (PMID 31092295, 2019).
encephalomyelitis (7 papers, 2015 to 2023). Inflammation of the brain and the spinal cord. "Progression of encephalomyelitis in the spinal cord was accompanied by increased expression of NLRP3, whereas loss of NLRP3, Casp1, ASC, or IL-1β in mice led to resistance to encephalomyelitis." (PMID 36669831, 2023). "Activation of NF-κB can regulate the release of TNF-α and IL-1β in the hippocampus, which is responsible for inflammatory diseases of the central nervous system." (PMID 36999158, 2023). "Treatment of mice with MCC950 blocked NLRP3 activation at a nanomolar concentration, which reduced IL-1β production and attenuated the severity of experimental encephalomyelitis in vivo." (PMID 36669831, 2023). "Moreover, in a model of encephalomyelitis, increased IL-1β levels paralleled a reduction in spinal GLT1 protein levels and IL-1β inhibitors prevented the decrease in GLT153." (PMID 29880832, 2018).
Graves’ orbitopathy (7 papers, 2011 to 2024). "CXCR6 was upregulated in the primary culture of orbital fibroblasts from patients with Graves’ orbitopathy, following treatment with pro-inflammatory cytokines IL-1β and TNF-α." (PMID 36658547, 2023). "The increased concentrations of tears’ inflammatory cytokines (IL-1β, IL- 6) and chemokine IL-8 in patients with active vs. inactive TAO (thyroid associated ophthalmopathy) supports this thesis." (PMID 24562464, 2014). "Recent studies have shown that laduviglusib can inhibit the activation of Akt, PI3K, nuclear factor-κB induced by IL-1β and TNF-α in cells modeling Graves’ orbitopathy." (PMID 38918688, 2024).
hemophagocytic lymphohistiocytosis (7 papers, 2018 to 2025). "Proinflammatory cytokines in the IL-1 family are regulators of IL-6 production, and high levels of IL-1β have been associated with cytokine storms and hemophagocytic lymphohistiocytosis." (PMID 36936774, 2023). "There is also evidence of an increase in IL-6 and IL-1β secretion in EBV-associated diseases, such as infectious mononucleosis and hemophagocytic lymphohistiocytosis." (PMID 36675141, 2023). "The large group of autoinflammatory disorders is further subdivided into IL-1β-mediated disorders, NF-κB dysregulation, type I interferonopathies, and hemophagocytic syndromes." (PMID 35126383, 2021).
Hypothermia (7 papers, 2009 to 2022). Reduced body temperature due to failed thermoregulation. "Hypothermia was associated with a reduction in: (i) immune cell infiltration, (ii) apoptosis, (iii) IL-1β and IL-6 mRNA up-regulation, and (iv) IL-1β protein expression (p<0.05)." (PMID 19855846, 2009). "Hypothermia and locomotor hypoactivity were induced by LPS>IL-1β>TNF-α>>IL-6." (PMID 23840908, 2013). "Hypothermia has been found to decrease inflammation by decreasing both the infiltration of polymorphonuclear cells and the production of a wide range of inflammatory proteins such as TNF-α, IL-1b, IL-6, and macrophage inflammatory protein-2." (PMID 27583464, 2016). "Hypothermia is known to occur in C57BL/6 mice when at ambient temperatures of 20-22°C and while the molecular underpinning of this hypothermic response is less clear it is nonetheless known that both systemic IL-1β and TNF-α can induce this response." (PMID 21586125, 2011).
ileus (7 papers, 2013 to 2023). Decrease in peristalsis in the absence of a mechanical bowel obstruction. "Moreover, EGC-muscularis MΦ crosstalk was observed in intestinal motility dysfunction caused by postoperative ileus, which was associated with muscularis MΦ elevated IL-1β levels." (PMID 37063880, 2023). "Although the role of IL-1β in the development of ileus in patients is less clear, IL-1β likely depresses gastrointestinal motility in humans as well." (PMID 35805922, 2022). "The development of ileus is likely to be multifaceted and IL-1β may be one of several inflammatory mediators that contribute to the development of ileus." (PMID 35805922, 2022). "The local inflammatory status may have a significant modulating role and correlations between ileus and increased systemic levels of proinflammatory cytokines (IL-1β, IL-6 and TNF-α) were also identified." (PMID 24137421, 2013). "We previously showed that the increased cyclical stretch of macrophages, which macrophages would experience in the intestinal wall during the development of edema or ileus, increases the secretion of inflammatory mediators such as CXCL1 and IL-1β." (PMID 37298834, 2023). "In rats with postoperative ileus, expression of TNF-α, IL-1β, IL-6, and IL-10 is reduced by Rb1 in ileum tissue, along with gastrointestinal transit increased, indicating a potent anti-inflammatory effect." (PMID 30402203, 2018). "In a rat with postoperative ileus, ginsenoside Rb1 reduces serum concentration of TNF-α, IL-1β, IL-6, and IL-10, indicating its anti-inflammatory effect." (PMID 30402203, 2018). "Alternatively, IL-1β may be upregulated during the development of inflammation leading to ileus, but may not directly affect gastrointestinal motility." (PMID 35805922, 2022). "In contrast, in another study, IL-1β, along with IL-6 and procalcitonin, was higher in patients with prolonged POI compared to patients who did not develop ileus following surgery for colorectal carcinoma." (PMID 35805922, 2022).
ischemia reperfusion injury (7 papers, 2009 to 2023). Adverse functional, metabolic, or structural changes in ischemic tissues resulting from the restoration of blood flow to the tissue (reperfusion), including swelling; hemorrhage; necrosis; and damage from free radicals. "Upon migration to the transplanted lung allograft, the recipient classical monocytes increase the pulmonary vasculature permeability through the release of IL-1β, allowing the neutrophils to extravasate and initiate the pathogenesis of ischemia-reperfusion injury." (PMID 36250462, 2022). "Supplementation with Ori reduced the levels of SOD2, CAT, MDA, ROS levels, and IL-1β, TNF-α in hind limb muscle tissue of ischemia–reperfusion injury mice, suggesting that Ori plays a protective role against oxidative stress and the inflammatory response." (PMID 37375489, 2023). "In an animal model of ischemia-reperfusion injury, pterostilbene improved cardiac function and reduced markers of oxidative stress and inflammation such as tumor necrosis factor-alpha (TNF-α), interleukin-1-beta (IL-1β) and myeloperoxidase activity." (PMID 29522491, 2018).
macular edema (7 papers, 2012 to 2025). "The aqueous humor levels of IL-1β, IL-6, IL-8, MCP-1, IP-10, and VEGF increased with increasing severity of macular edema." (PMID 25923230, 2015). "The present study showed that aqueous levels of IL-1β, IL-6, IL-8, IP-10, MCP-1, and VEGF were increased in patients with postcataract surgery macular edema and were positively correlated with FCPT 4 weeks following cataract surgery in diabetic patients." (PMID 25811020, 2015). "TNF-α and IL-1β are the key drivers of retinal endothelial dysfunction in non-infectious uveitis, leading to macular oedema and vascular leakage." (PMID 40305201, 2025). "This study showed that intraocular IL-6, IL-8, IL-1β, TGF-β, bFGF, SAA, and VEGF were strikingly higher in patients with macular edema than in the control patients, regardless of whether this was due to CRVO or BRVO." (PMID 23861862, 2013).
oral lichen planus (7 papers, 2015 to 2024). Oral lichen planus is a chronic inflammatory oral condition of unknown aetiology characterized by T-cell-mediated chronic immune response and abnormal epithelial keratinization cycle. "The study by Zheng and co-workers found that P. melaninogenica can adhere to the cell surface, invade macrophages, and increase IL-1β, IL-6, and TNF-α expression in oral lichen planus." (PMID 37887710, 2023).
Pruritus (7 papers, 2016 to 2025). Pruritus is an itch or a sensation that makes a person want to scratch. "Our study suggests that in CCCA patients, pruritus is associated with active scalp inflammation, specifically IL-1β." (PMID 37965352, 2023). "Given that Nlrp3-knockout (KO) mice exhibited increased scratching behavior in a DNFB-induced chronic itch model, we further investigated whether IL-18 or IL-1β plays a vital role in NLRP3 inflammasome activation." (PMID 39867900, 2024). "In addition, studies using itch-deficient (Itch−/−) mice showed enhancement of phosphorylation of p38α in skin lesions, and the levels of proinflammatory cytokines such as TNF-α and IL-1β were increased in the skin of Itch−/− mice." (PMID 35798870, 2022). "Simultaneously, CGRP stimulates keratinocyte proliferation but also prompts the release of CGRP, interleukin-1β (IL-1β), IL-6, and tumor necrosis factor-alpha (TNF-α), leading to conditions such as rash and pruritus." (PMID 39144633, 2024).
pustular psoriasis (7 papers, 2019 to 2025). "Another genetic defect associated with pustular psoriasis is the IL36RN mutation, which decreases activity of the IL-36R antagonist and increases IL-36R signaling, leading to expression of IL-1β and CXCL8." (PMID 38448036, 2024). "Recently, it was reported that patients with severe pustular psoriasis showed substantial clinical response to anti-IL-1β gevokizumab and canakinumab, suggesting a critical involvement of IL-1β in GPP pathogenesis." (PMID 34567002, 2021). "Pustular psoriasis is characterized by the increased expression of IL-1β, IL-36α, and IL-36γ transcripts, which have been found in pustular psoriasis compared to psoriasis vulgaris." (PMID 30909615, 2019). "Canakinumab, targeting IL-1β, has been used in the treatment of pustular psoriasis." (PMID 40722833, 2025). "Thus, IL-1 inhibitors particularly IL-1β could be potentially efficacious in management of psoriasis especially pustular psoriasis, though larger studies are needed." (PMID 35265634, 2022).
relapsing-remitting MS (7 papers, 2013 to 2025). "Our study showed that both interleukin-1 beta (IL-1β) and interleukin-1 receptor antagonist (IL-1Ra) levels in CSF were significantly lower in patients with newly diagnosed relapsing-remitting multiple sclerosis (RRMS) than in healthy controls." (PMID 39000506, 2024). "Another pro-inflammatory cytokine IL-1β is also significantly released into the cerebrospinal fluid of MS patients in the active disease state, and higher levels are closely related to a more severe progression and poor prognosis of patients with a relapsing-remitting MS." (PMID 31623610, 2019). "Furthermore, fluoxetine decreased the production of IL‐1β, IL‐6, and IL‐17 by activated CD4+ and CD8+ T-cells, suggesting an anti-inflammatory effect of treatment with fluoxetine on Th17-immune response in relapsing-remitting MS patients with MDD." (PMID 36189272, 2022).
retinal ischemia (7 papers, 2016 to 2024). A ischemic disease that involves the retina. "Retinal ischemia increases compensatory angiogenesis, tissue remodeling and inflammation, presumably mediated by elevated expression of IL-6, IL-1β, TNFα and VEGF." (PMID 36983353, 2023). "Modulates the overexpression of GFAP in in vivo models of retinal ischemia and inhibits overactivation of NF-κB, IL-1β, and Cox-2 in Müller cells." (PMID 34439904, 2021). "Additionally, intracellular adhesion molecules, along with endothelial and glial cells, induce the upregulation of VEGF, TNF-α, IL-6, and IL-1β, leading to retinal ischemia and hypoxia." (PMID 39634174, 2024). "Furthermore, we have also reported that caspase-8 (CASP8)-induced NLRP3 promotes IL-1β processing during innate immune responses in an IOP-induced retinal ischemia model." (PMID 32295623, 2020). "A recent study showed that inhibition of caspase-1 reduced IL-1β expression to baseline post retinal ischemia injury, while inhibition of caspase-8 further down-regulated the level of IL-1β, suggesting that IL levels could be regulated by both NLRP3-dependent and other pathways." (PMID 26893104, 2016). "Given these novel findings, we have determined that IL-1β is a central factor enhancing CASP8-HIF-1α signaling to subsequently increase NLRP3/NLRP12/NLRC4 activation and to initiate pyroptosis during retinal ischemia." (PMID 32295623, 2020). "As in whole blood, it has been shown that caffeine does not change the LPS-induced secretion of IL-10, IL-6, and IL-1β, while reduced mRNA expression of IL-6, IL-12, and IL-3 has been found in LPS-activated RAW264.7 cells or retinal ischemia/reperfusion-induced IL-6 and IL-1β secretion by microglia." (PMID 34371919, 2021).
retinitis pigmentosa (7 papers, 2017 to 2025). Retinitis pigmentosa (RP) is an inherited retinal dystrophy leading to progressive loss of the photoreceptors and retinal pigment epithelium and resulting in blindness usually after several decades. "Higher IL-1β protein levels are also associated with photoreceptor cell death and diminished visual fields in retinitis pigmentosa." (PMID 35576057, 2022). "One study reported that microglia in mouse models of retinitis pigmentosa (RP) and human RP contribute to photoreceptor degeneration via non-cell-autonomous mechanisms involving primary phagocytosis and inflammatory cytokine production, particularly IL-1b." (PMID 34063002, 2021). "Inhibition of IL1β can decrease microglial reactivity, which correlates to a reduction in photoreceptor apoptosis and preservation of retinal function in a mouse model of retinitis pigmentosa." (PMID 31170999, 2019). "Several studies have also indicated that IL-1β is secreted by microglia in photo-oxidative damage, as well as in models of neovascular AMD, retinitis pigmentosa, and retinal detachment." (PMID 28438165, 2017).
acute lymphoblastic leukemia (6 papers, 2017 to 2025). Leukemia with an acute onset, characterized by the presence of lymphoblasts in the bone marrow and the peripheral blood. "One of the related studies of IL-1β is with acute lymphoblastic leukemia, in which IL-1β is known to induce NF-κB activation; more importantly, in KRAS mutant cancer cells, it leads to drug resistance and increased cancer progression." (PMID 36840009, 2023). "In acute lymphoblastic leukemia, KRAS (Kirsten rat sarcoma viral oncogene homolog) G12D mutation is responsible for the binding of cAMP response element binding (CREB) on IL1B promoter and increases the expression of IL-1β in these cells." (PMID 32635472, 2020). "Acute lymphocytic leukemia (ALL) cells were reported not to express IL-1β." (PMID 28152513, 2017). "The novelty of this work is the association of DAMPs (HMGB1) and inflammatory mediators (IL-8, IL-10, IL1-β, and MCP-1) in the development of systemic inflammatory response (SIRS) in pediatric patients with newly diagnosed acute lymphoblastic leukemia (ALL) and no apparent clinical infection." (PMID 40868835, 2025).
Ascites (6 papers, 2012 to 2025). Accumulation of fluid in the peritoneal cavity (between the layers of the peritoneum that lines the abdomen). "In addition, another theory is that substances such as VEGF that raise capillary permeability and some inflammatory cytokines including interleukin (IL)-1β, IL-6, and IL-8 are possible etiologies of ascites and hydrothorax formation." (PMID 27160723, 2016). "The association between dietary fiber intake and interleukin (IL)-1β, IL-6, tumor necrosis factor-α (TNF-α), monocyte chemoattractant protein-1 (MCP-1), B-cell activating factor (BAFF), and plasminogen activator inhibitor-1 (PAI-1) levels in serum and peritoneal effusion." (PMID 40735439, 2025). "Furthermore, previous studies showed deregulation of different mediators, illustrated by the upregulation of pro-inflammatory cytokines such as IL1β, IL6, TNFα, MIP1α, RANTES, and IFNγ in peritoneal effusions and serum samples of FIP clinical cases." (PMID 28388950, 2017).
Ataxia (6 papers, 2010 to 2024). Ataxia refers to impaired coordination of voluntary muscle movement. "Neuroinflammation, including that caused by the release of cytokines such as IL-1β, can be either neuroprotective or deleterious in a broad range of pathogenic contexts including the ataxias." (PMID 37237366, 2023). "In the cerebellum, where KA was demonstrate to induce ataxia partially via elevation of IL-1β, exogenous IL-18 was protective and played a positive role in the recovery from kainate-induced ataxia." (PMID 20113500, 2010). "Indeed, direct injection of IL-1β into the cerebellum of wild-type mice is sufficient to induce Purkinje cell pathology and cerebellar ataxia." (PMID 37237366, 2023). "The first being the recognition that Il-18 and Il-1β, when their combined action was tested, may have antagonizing effects such as those occurring in fever and in kainate-induced cerebellar ataxia." (PMID 20113500, 2010). "In another study, chemogenetic activation of microglia in the cerebellar vermis in vivo resulted increased firing of Purkinje neurons, increased expression of TNF-α, IL-1β and CCL-2 and produced ataxia in mice." (PMID 37950146, 2024). "At 3 weeks after the 3-AP injection, we did not observe any significant changes in the expression of Iba1, Il1b, Il18, or iNos, indicating no microglial and pro-inflammatory responses during the chronic phase of ataxia." (PMID 37047062, 2023). "Also, local microinjection of IL-1β into the cerebellum in vivo produced ataxia, whereas local microinjection of IL-6 did not, suggesting a role for IL-1β in ataxia." (PMID 37950146, 2024). "IL-1β activity was not required for the ERP, as LT-challenged B6Nlrp1b(129S1);IL-1R−/− animals showed ataxia and hypothermic responses that were indistinguishable from B6Nlrp1b(129S1) mice." (PMID 22241984, 2011).
autoimmune myocarditis (6 papers, 2004 to 2024). Autoimmune myocarditis is an autoimmune disease that affects the heart. "Autoimmune myocarditis persists and progressively evolves into DCM with the involvement of cardiac macrophages, fibroblasts, and cytokines, in which cytokines such as IL-1β and IL-6 promote DCM at this stage." (PMID 36827455, 2023). "In addition, the proinflammatory markers, c-fos, IL-6, iNOS, and IL-1β, were upregulated only in the hearts of male but not female rats with autoimmune myocarditis." (PMID 35754849, 2022).